CADM1 (cell adhesion molecule 1)
Diseases named in the same sentence as CADM1 in open-access papers (continued):
Sharing a sentence is not in itself a finding about the gene and the disease.
tumor (continued). "In esophageal squamous cell carcinoma, CADM1 expression is related with the tumor development and the advanced tumor–node–metastasis stage." (PMID 33419290, 2020). "Encouragingly, circulating exosome miR‐148a was found in serum and promoted tumour progression by targeting CADM1 to activate STAT3 pathway, suggesting its clinical value." (PMID 32412186, 2020). "This adhesion molecule has been identified as a suppressor gene of tumors, and CADM1-transfected large lung cell cancer cells showed decreased development of the tumor." (PMID 33419290, 2020). "CADM1 has the potential to activate tumor lysates by NK cells and strong IFN-γ production by CD8+ T cells, indicating that CADM1 acts as the communication molecule for immune cells to invoke their immune ability against tumors." (PMID 33419290, 2020). "The detailed functions of intracellular domain of CADM1 are little known, therefore it is desirable for it to be clarified in various cells and tumor cells." (PMID 33419290, 2020). "CADM1, a member of the cell adhesion molecule family, has been proven to be a tumor suppressor in many cancers, including breast cancer, esophageal squamous cell carcinoma, and hepatocellular carcinoma." (PMID 31334110, 2019). "In MM, it was reported that the expression of CADM1 was also significantly downregulated and functions as a tumor suppressor by suppressing matrix metalloproteinases (MMPs) in MM." (PMID 31334110, 2019). "CADM1 (also known as TSLC1, NECL-2, IGSF4, SynCAM1) acts as a tumor suppressor in a variety of human cancers and has been proposed as a cell surface marker for ATLL." (PMID 31835460, 2019). "On the other hand, SETDB2 overexpression is associated with poor prognoses and tumour progression in gastric cancer through H3K9me3-mediated silencing of tumour suppressor genes WWOX and CADM1." (PMID 30850015, 2019). "Although the role of CADM1 as a tumor suppressor in solid tumors is partially known, its role in oncogenic virus-mediated tumors is poorly understood." (PMID 29698475, 2018). "Although many studies have suggested that CADM1 functions as a tumor suppressor, our findings indicate that CADM1 functions as an oncogene/tumor promoter in KSHV-infected cells." (PMID 29698475, 2018). "Hypermethylation of host cell tumor suppressor genes including E-cadherin (CDH1), Cell Adhesion Molecule 1 (CADM1) and Death-Associated Protein Kinase 1 (DAPK1) was reported in recent studies." (PMID 28881717, 2017). "Unfortunately, this (CADM1) protein has lower expression in tumor samples compared to normal lung samples." (PMID 29371917, 2017). "CADM1 was originally identified as a tumor suppressor gene that suppressed tumor growth in nude mice and suppressed cancer metastasis by regulating cell adhesion." (PMID 28414795, 2017). "Using tumour xenograft studies, we demonstrate that the extracellular domain of CADM1 regulates SqCC progression via generation of a HER2-ITGα6β4-CADM1 complex at the cell surface that inhibits HER2-ITGα6β4 mediated STAT3 phosphorylation." (PMID 27035095, 2016). "In lung adenocarcinoma CADM1 inhibits tumour cell proliferation via cytoplasmic band 4.1 and MAGuK protein interactions." (PMID 27035095, 2016). "Analysis of lung (Bhattacharjee), head and neck (TCGA), oesophagus (Su), and cervical SqCC (Zhai) datasets revealed significant reductions in CADM1 expression in all tumour samples relative to controls." (PMID 27035095, 2016). "We demonstrate that the extracellular domain of CADM1 restricts tumour growth and metastases by interacting with HER2 and integrin α6β4 at the cell surface." (PMID 27035095, 2016). "Here, we use gene transduction and human tumor xenograft assays to establish that the tumour suppressor Cell adhesion molecule 1 (CADM1) inhibits SqCC proliferation and invasion, processes fundamental to disease progression." (PMID 27035095, 2016). "Using transwell migration assays, we assessed the in vitro migration potential of CADM1 expressing tumour cells." (PMID 27035095, 2016).
tumor (continued). "Longitudinal imaging demonstrated reduced SqCC growth in CADM1 expressing tumours relative to controls (p = 0.0001)." (PMID 27035095, 2016). "We subsequently show that treating CADM1 null tumours with the JAK/STAT inhibitor ruxolitinib mimics CADM1 gene restoration in preventing SqCC growth and metastases." (PMID 27035095, 2016). "Consistent with our in vitro results, longitudinal and open imaging demonstrated that CADM1-ΔCP tumours grew at a reduced rate and with fewer metastases per mouse when compared with CADM1-ΔEC tumours (*p < 0.01; n = 6 animals/cell type)." (PMID 27035095, 2016). "CADM1/TSLC1 was detected in 236 (80.5%) tumor tissues and 19 (8.0%) paired adjacent normal esophageal tissues." (PMID 26880895, 2016). "In this study we use patient samples, cell lines, and human tumour xenograft models to define a key functional role for CADM1 in SqCC progression." (PMID 27035095, 2016). "Ito and colleagues reported that loss of CADM1/TSLC1 expression plays an important role in tumor growth, cell motility, and invasion and is associated with aggressive tumor behavior in ESCC." (PMID 26880895, 2016). "As above, we used a human tumour xenograft model to assess CADM1-ΔCP and CADM1-ΔEC growth and metastases in vivo." (PMID 27035095, 2016). "Cell adhesion molecule 1 (CADM1; also known as TSLC1, IGSF4 or NECL2) is encoded by chromosomal region 11q23 and was first identified as a tumor suppressor gene in non-small cell lung cancer (NSCLC)." (PMID 25774694, 2015). "CADM1 expression performed comparably to the SE score in a meta-analysis, however, it was outperformed by pathological tumour stage (CADM1 expression vs stage: p = 0.03)." (PMID 25793737, 2015). "The expression of CADM1 is frequently silenced in several cancers; however, it is critical for HTLV-1 associated ATL tumor cell survival." (PMID 25774694, 2015). "Reduced CADM1 expression disrupts cell-cell adhesion in epithelial cells and triggers tumor cell invasion and metastasis." (PMID 25845528, 2015). "CADM1 is a tumor suppressor belonging to the immunoglobulin superfamily of cell adhesion molecule and forms a cell adhesion complex with an actin-binding protein, 4.1B, and a scaffold protein, MPP3, in the cytoplasm." (PMID 25780926, 2015). "The cell adhesion molecule 1 (CADM1) gene encodes a member of the immunoglobulin superfamily and is one of the crucial tumor suppressors involved in cell adhesion." (PMID 25845528, 2015). "Considering that the disruption of cell-cell adhesion in epithelial cells triggers tumor cell invasion and metastasis, CADM1 is one of the crucial tumor suppressors involved in cell adhesion like E-cadherin." (PMID 24503895, 2014). "Expression of CADM1 is down-regulated in various carcinomas, and it is widely accepted that CADM1 is a tumor suppressor through its cell adhesive property." (PMID 24503895, 2014). "The methylation pattern of CADM1 was furthermore characterized, and CADM1 protein expression was validated in two large independent primary tumor cohorts as well as in BCBM samples and correlated with clinico-pathological parameters." (PMID 24833255, 2014). "CADM1 expression is detected by immunohistochemistry which is more accurate because pathologists can directly determine the expression of CADM1 in tumor tissues." (PMID 25159494, 2014). "Here we demonstrate that expression of Cadm1 in two independent cell lines resulted in either specific metastasis suppression or tumor suppression accompanied by a reduction in metastasis." (PMID 23028344, 2012). "With the exception of the Boersma set, high Cadm1 expression consistently correlated with significantly improved survival in estrogen receptor (ER) positive tumor datasets." (PMID 23028344, 2012).
tumor (continued). "In this manuscript, we use in vivo modeling to show that high expression of Cadm1 inhibits pulmonary metastasis, while knockdown of Cadm1 promotes the metastatic capability of tumor cells." (PMID 23028344, 2012). "Our data show a novel function for Cadm1 in suppressing metastasis by sensitizing tumor cells to immune surveillance mechanisms, and this is the first report of a heritable metastasis susceptibility gene engaging tumor non-autonomous factors." (PMID 23028344, 2012). "Thirty days post-injection mice were euthanized and primary tumors were resected and weighed to assess the effect of Cadm1 on primary tumor growth." (PMID 23028344, 2012). "We confirm that Cadm1 is indeed a bona fide tumor suppressor gene and provide new insights into genetic partners that co-operate in tumorigenesis when Cadm1-expression is lost." (PMID 22553910, 2012). "The engagement of Cadm1 on tumor cells and Crtam on CD8+ T cells has been reported to induce interferon-γ production of CD8+ T cells." (PMID 23028344, 2012). "Cadm1 was previously identified as a tumor suppressor in lung adenocarcinoma, and reductions in its expression have been associated with poor survival in numerous cancer types." (PMID 23028344, 2012). "This approach identified CADM1 as a strong candidate 11q tumour suppressor gene with prognostic power, which possibly exerts its effect through haplo-insufficiency." (PMID 18559103, 2008). "The GARP expression on the cell surface was positively correlated with the tumor population size (CD4+/CADM1+/CD7−; “N” fraction) and soluble IL-2R, suggesting that ATL cases with high GARP+ ATL cells may be clinically more aggressive." (PMID 40759773, 2025). "Among these, CADM1 could be used as a tumor suppressor gene to promote apoptosis and inhibit the proliferation of cancer cells in multiple tumors." (PMID 41383963, 2025). "And the results of qRT-PCR showed us that the expression of CADM1_CADM1 in PTC was down-regulated and overexpression of CADM1 could suppresses tumor cell invasion migration." (PMID 36523593, 2022). "Therefore, miR-424-5p downregulates the progression of LSCC by downregulating the level of CADM1 and promotes tumor proliferation, invasion and migration." (PMID 35409396, 2022). "High expression of CADM1 in small intestinal GISTs possibly resulting in promoting tumor invasion and tumor growth on the peritoneum (peritoneal dissemination) might explain the more aggressive behavior and worse prognosis of small intestinal GISTs." (PMID 34257559, 2021). "CADM1 was ordinally expressed in the invasive front of the tumor." (PMID 34064472, 2021). "Although our study could not conduct an in vitro study to confirm the actual impact of the migration of tumor cells, these results suggest that CADM1 might be a key molecule for predicting tumor prognosis in cSCC." (PMID 34064472, 2021). "Also, we measured total WNT5A mRNA levels by qPCR in the tumor cell fraction (CD4 + /CD7 − /CADM1 +) of an HTLV-1 carrier, a smoldering-type ATL patient, and 3 acute-type ATL patients, which were concentrated by the HAS-Flow method." (PMID 33603066, 2021). "Because our study identified CADM1 as one of the independent prognostic indicators by a multivariate analysis, we suggest that CADM1 targeted therapy may be beneficial for tumor treatment." (PMID 34064472, 2021). "Although this study could not elucidate a more detailed molecular mechanism of the impact of CADM1 on tumor metastasis and invasion, it might be possible to predict tumor prognosis by examining the pattern of CADM1 expression in the tumor." (PMID 34064472, 2021). "In addition, non-coding sequences, such as lncRNAs and miRNAs, participate in regulating tumor progression along with CADM1." (PMID 34395444, 2021). "Therefore, it is important to distinguish the direct impact of CADM1 on tumor prognosis by excluding the effect of tumor differentiation." (PMID 34064472, 2021).
tumor (continued). "Furthermore, immunohistochemistry suggests that CADM1 expression is low, and CADM1 promoter methylation relates to tumor progression and cancer stage." (PMID 34395444, 2021). "In addition, some long non-coding RNAs (lncRNAs) or miRNAs directly or indirectly act on CADM1 to regulate tumor growth and motility." (PMID 34395444, 2021). "In addition, CADM1 binds HER2 through its extracellular domain and activates HER2 as well as CADM1 inhibited, which enhances tumor metastasis by activating the downstream STAT3 signaling pathway." (PMID 34395444, 2021). "Upregulated CADM1 promotes tumor cell apoptosis and inhibits malignant proliferation." (PMID 34395444, 2021). "However, this is contrary to previous studies that showed that CADM1 acts as a tumor suppressor in most solid tumors." (PMID 34395444, 2021). "Our results suggested that miR-486 could act as a tumor promoter by targeting CADM1 and be a potential therapeutic target for the treatment of OC." (PMID 34395181, 2021). "CADM1 is a transmembrane glycoprotein with several tumour suppressor roles including modulation of cell cycle progression, induction of apoptosis, activation of immunosurveillance responses as well as enhancement of cell–cell adhesion through its extracellular domain." (PMID 33167358, 2020). "Especially, CADM1 contributes to bone marrow-derived cells to the communication with other type cells and promotes cell migration as a scaffolding molecule, which also contributes to cutaneous lymphoma to develop the tumor environment." (PMID 33419290, 2020). "We then performed quantitative real-time PCR (qRT-PCR) analysis for four cell surface receptor genes (PTN, CD24, BMP7, and CADM1), because their protein products are easily detectable by molecular diagnosis and are also related to cell survival, proliferation, or tumor growth." (PMID 33298865, 2020). "The expression of CADM1 is not only an activation marker of SS tumor cells, but also the possible involvement of CADM1 as a scaffolding molecule in the epidermotropic infiltration of tumor cells into epidermal keratinocytes and penetration through the basement membrane zone." (PMID 33419290, 2020). "The expression of CADM1 is low in liver cancer cells and tumor tissues." (PMID 33419290, 2020). "Our analysis reported that this mechanism of tumor suppression could be mediated by CADM1 and its receptor CRTAM." (PMID 33155039, 2020). "A reduction was shown for mRNA and protein amounts of CADM1 in GBM tumor tissues." (PMID 32746854, 2020). "Loss of CADM1 expression by promoter hypermethylation or loss of heterozygosity (LOH) has been strongly linked to poor prognosis, tumour progression, invasion and metastasis in many cancers, and has thus become an attractive diagnostic and prognostic biomarker." (PMID 33167358, 2020). "Interestingly, tumor cells expressing Cell Adhesion Molecule 1 (CADM1), a cell adhesion molecule directly induced by the EMT-promoting TGF-β pathway, are susceptible to NK cell-mediated cytotoxicity." (PMID 31075939, 2019). "Moreover, CADM1 expression enhances tumor growth and invasion of ATLL cells in a xenograft mouse model." (PMID 30837480, 2019). "Indeed, it has been shown that cell adhesion molecules, such as E-Cadherin, and the Ig superfamily member CADM1, can act as tumour suppressors mainly through contact inhibition of cell proliferation." (PMID 30901340, 2019). "To establish whether CADM1 inhibits SqCC progression in vivo we developed a human tumour xenograft model in which control or CADM1 expressing A431 cells were transplanted into immunocompromised mice by intravenous tail vein injection (n = 8 mice/tumour type)." (PMID 27035095, 2016). "Finally, in colon adenocarcinoma CADM1 regulates hemidesmosome stability by increasing integrin α6β4 interactions, thereby reducing tumour cell motility." (PMID 27035095, 2016). "Thus, the mechanisms by which CADM1 regulates disease progression are highly dependent on the tumour and tissue type in which it is expressed." (PMID 27035095, 2016).
tumor (continued). "To establish whether endogenous CADM1 expression could influence in vivo SqCC sensitivity to JAK/STAT inhibition we generated human tumour xenografts using the SqCC lines SCC9 and SCC13." (PMID 27035095, 2016). "The functional activities of CADM1 that have been described to-date include suppression of tumor growth (such as NSCLC), activation of NK or CD8+ T cells by serving as a tumor antigen, regulation of cell-cell interactions, and regulation of proper T-cell functions." (PMID 25774694, 2015). "Intriguingly, although CADM1 functions as a tumor suppressor in NSCLC, it may function as an oncoprotein in ATL cells." (PMID 25774694, 2015). "Together, the results suggest that Cadm1 may have both tumor suppressive and metastasis suppressive activities which may depend on the level of Cadm1 expressed." (PMID 23028344, 2012). "Since these cells were injected directly into the venous circulation and likely seeded the lungs immediately after injection, they had little time to lose Cadm1 expression suggesting that tumor cells with lower overall Cadm1 expression upon injection were selected for colonization." (PMID 23028344, 2012). "This suggests that T cell mediated immunity may be critical for the tumor and metastasis suppressive effects of Cadm1." (PMID 23028344, 2012). "In contrast, high Cadm1 levels only significantly correlated with improved survival in ER negative patients in the Boersma dataset, suggesting that any effect Cadm1 levels may have on tumor progression are primarily relevant to ER positive tumors." (PMID 23028344, 2012). "We have shown that Cadm1 may regulate metastasis by sensitizing tumor cells to surveillance by the immune system." (PMID 23028344, 2012). "Significant reductions in pulmonary metastasis were also observed by intravenous injection of tumor cells into the tail-vein, a model that assays tumor cell colonization of the lung, suggesting that the effect of Cadm1 on metastasis operates downstream of local invasion and intravasation." (PMID 23028344, 2012). "Cell adhesion molecule 1 (CADM1) from an Ig superfamily member was also reported to have tumor suppressor activity in numerous cancer forms like ovarian, breast, and pancreatic, and in all those cases, the loss of CADM1 expression was recognized as a marker of tumor progression and metastasis." (PMID 39156005, 2024). "Thus, CADM1 might mediate its tumor suppressor function against EBV-transformed B cells during XIAP deficiency in a cell extrinsic function that is independent of CD8+ T cells." (PMID 36270981, 2022). "Among them, cell adhesion molecule 1 (CADM1) is an apoptosis-inducing tumor suppressor that is inactivated by methylation in a variety of tumor types, which may play a role in chemotherapy-induced cell death in AML, but the other 5 genes’ role was rarely reported in AML." (PMID 36164519, 2022). "However, in individual tumors, such as ATLL and SCLC, CADM1 promotes tumor progression." (PMID 34395444, 2021). "Thus, epigenetic changes in CADM1 do play a role in tumor regulation." (PMID 34395444, 2021). "Therefore, the CADM1/HER2/STAT3 axis has broad prospects for the treatment of tumor metastasis." (PMID 34395444, 2021). "Moreover, CADM1 expression has a significant relationship with tumor differentiation." (PMID 34064472, 2021). "In addition, a genome-wide study also suggested that CADM1 played a role in tumor development." (PMID 34064472, 2021). "In addition, a genome-wide study also suggested that CADM1 plays a role in tumor development." (PMID 33419290, 2020). "These authors found that some of these genes are also involved in spermatogenesis (much like our CADM1 example), and concluded that genomic conflict between tumor suppression and the advantage of avoiding apoptosis during spermatogenesis may explain the selection on cancer genes." (PMID 28482049, 2017).